VTN (vitronectin)
Diseases named in the same sentence as VTN in open-access papers (continued):
Sharing a sentence is not in itself a finding about the gene and the disease.
COVID-19 (6 papers, 2022 to 2025). A disease caused by infection with severe acute respiratory syndrome coronavirus 2. "We observed a significant upregulation of VTN in the plasma of PLWH with COVID-19." (PMID 40568587, 2025). "It was observed in COVID-19 patients that plasminogen activator inhibitor-1 (PAI-1), vitronectin, plasminogen, and tPA were elevated and fibrin clots formed from COVID-19 patient plasma showed altered fibrin network structures with elevated cross-linking and shorter fibrin fibres." (PMID 36998202, 2023). "Several proteins related to the complement cascade have been shown to be dysregulated in PLWH with COVID-19; for example, complement factor D (CFD), mannan-binding lectin serine protease 2, and VTN levels were significantly elevated compared to those in PLWH and HCs." (PMID 40568587, 2025). "PAI-1 and its cofactor, vitronectin, are significantly elevated in patients with COVID-19 as compared with those with a non-COVID-19 respiratory infection or healthy control groups." (PMID 37189799, 2023).
liver fibrosis (6 papers, 2015 to 2025). "Vitronectin has been extensively studied in the frame of liver fibrosis in chronic liver diseases such as viral hepatitis B and C infections and HCC." (PMID 29463024, 2018). "Vitronectin stimulates dermal healing, is transiently upregulated during scar formation, and has been identified as a marker of hepatic fibrosis." (PMID 26194911, 2015).
fibrosis (5 papers, 2021 to 2025). the formation of excess fibrous connective tissue in an organ or tissue in a reparative or reactive process. "Top novel candidate genes with high entropy values include VTN, FGB and FGG, which are associated with changes observed in fibrosis under chronic liver damage condition." (PMID 36944690, 2023). "In the present study, employing 2 distinct murine fibrosis models and VTN-deficient mice, we found that VTN is not required for PAI-1 to drive lung scarring." (PMID 40299646, 2025). "Since it is not feasible to apply mass spectrometry techniques to the clinical setting, the results related to vitronectin were further validated with a preliminary ELISA in urine samples from a limited number of kidney-transplanted patients with different grades of fibrosis." (PMID 33275196, 2021). "Hence, VTN(381–397 a.a.) cannot be defined as a specific marker of OA, since it is present in other rheumatic diseases, but its presence can be related to the typical ECM alteration present in fibrosis." (PMID 33526813, 2021).
hepatocellular carcinoma (5 papers, 2006 to 2025). A malignant tumor that arises from hepatocytes. "In conclusion, the present study highlighted the critical roles of MET, TIMP1, and VTN in the progression of MVI in hepatocellular carcinoma, underscoring their previously unreported contributions to this process." (PMID 39944086, 2025). "Fragmented vitronectin is increased in the serum of hepatocellular carcinoma patients, but mRNA expression of vitronectin is paradoxically decreased in carcinoma tissue." (PMID 19400944, 2009). "While vitronectin has previously been shown to be tyrosine-sulfated in human hepatoma-derived cell line Hep G2 and human plasma, its tyrosine sulfation status in the human RPE is unknown." (PMID 25136834, 2014). "Vitronectin is also a major component of the stroma of primary hepatocellular carcinoma (HCC) and metastatic hepatic tumours, including colorectal hepatic metastases (CHM)." (PMID 17088900, 2006). "Thus, we investigated the ability of vitronectin to support migration and adhesion of TIL isolated from hepatocellular carcinoma and colorectal hepatic metastases." (PMID 17088900, 2006).
nasopharyngeal carcinoma (5 papers, 2018 to 2021). A carcinoma arising from the nasopharyngeal epithelium. "COL1A1, ITGB4 and VTN have been associated with radioresistance in different types of cancer, such as nasopharyngeal carcinoma, esophageal squamous cell carcinoma and head and neck cancer." (PMID 34211843, 2021). "In addition, LPLUNC1 can inhibit the migration and invasion of NPC cells and inhibits radioresistance in nasopharyngeal carcinoma by inhibiting VTN expression." (PMID 30886235, 2019). "In nasopharyngeal carcinoma, VTN was identified as once of BPIFB1-interacting proteins and could be reduced by BPIFB1, leading to less formation of VTN-integrin αV complex, suppressing the EMT process, and inhibition of the activation of downstream FAK/Src/ERK signaling pathway." (PMID 30819137, 2019). "For example, the cell adhesion molecule vitronectin (VTN) is an important oncogene, and the dysregulation of its expression promotes the migration and invasion of nasopharyngeal carcinoma (NPC) as well as resistance of the NPC cells to radiotherapy." (PMID 29688867, 2018).
Alzheimer disease (4 papers, 2008 to 2026). A progressive, neurodegenerative disease characterized by loss of function and death of nerve cells in several areas of the brain leading to loss of cognitive function such as memory and language. "Vitronectin is known to accumulate in extracellular deposits in the eye and brain that are associated with macular degeneration and Alzheimer disease, respectively." (PMID 18939994, 2008). "Moreover, evidence suggests that VTN is associated with neurodegenerative diseases, such as Alzheimer’s disease, but its function has not been fully understood." (PMID 36293243, 2022). "Starting at month-6, this upregulated protein set includes neuroinflammatory-related proteins like complement C4-B, glial fibrillary acidic protein, protein-arginine deiminase type-2, vimentin, and vitronectin that have long been associated with Alzheimer’s disease." (PMID 35944844, 2022). "VTN is closely related to Alzheimer’s disease, while it has been reported to exist in senile plaques and neurofibrillary tangles in the entorhinal cortex of AD, and its receptor is present in glial cells of senile plaques." (PMID 36293243, 2022). "Studies showed that, in vitro, VTN inhibits β-amyloid aggregation to form a fibrous amyloid, which is the main feature of Alzheimer’s disease (AD)." (PMID 36293243, 2022). "In order to assess the presence of vitronectin in extracellular deposits, we examined Alzheimer disease brain." (PMID 18939994, 2008). "In addition, VTN has been reported to be related with TREM2 in patients with Alzheimer’s disease, which is an important gene for maintaining MG metabolism." (PMID 36293243, 2022).
cervical cancer (4 papers, 2020 to 2024). A primary or metastatic malignant neoplasm involving the cervix. "In order to explore the roles of VTN in cervical cancer cells, our group transfected pCDH-VTN to enhance VTN expression and transfected VTN shRNA to inhibit VTN levels in Hela and C33A." (PMID 39717749, 2024). "In this study, we aimed to determine the molecular function of VTN and its potential mechanism in cervical cancer (CC)." (PMID 39717749, 2024). "Overexpression of VTN in cervical cancer cells led to a decrease in the protein expression levels of ZO-1 and E-cadherin and an increase in the expression levels of β-catenin and N-cadherin." (PMID 39717749, 2024). "VTN might be a potential prognostic marker and meaningful new therapeutic target for cervical cancer." (PMID 39717749, 2024). "VTN plays a tumor-promoting role in CC by promoting the EMT of cervical cancer cells." (PMID 39717749, 2024). "Hence, we deduced that VTN might promote cervical cancer by EMT." (PMID 39717749, 2024). "Some of the most promising cervicovaginal fluid-based biomarkers for cervical cancer found until now are ACTN4, VTN, ANXA1, ANXA2, CAP1, and MUC5B." (PMID 35645371, 2022). "Vitronectin, or VTN, is another potential protein biomarker for cervical cancer in CVF." (PMID 35645371, 2022).
colon cancer (4 papers, 1999 to 2024). "Interestingly, co-incubation of CT-26 cells with SB225002 abolished CXCL2-induced adhesion of colon cancer cells to vitronectin, fibronectin, collagen IV, laminin I and fibrinogen." (PMID 34115261, 2021). "Differential gene expression analysis further showed that the extracellular matrix component vitronectin (VTN) is highly expressed in liver metastases but not in primary colon tumors, in line with previous findings." (PMID 38473429, 2024). "Under the physiological shear condition, cultured colon cancer cells bound to laminin (LM), but not to fibronectin or vitronectin." (PMID 10471041, 1999). "To assess how the mouse model for metastatic colon cancer described in this report reflects these site-specific differences in the tumor microenvironment, we performed immunohistochemistry analysis to detect blood vessels (CD31), macrophages (CD68), and vitronectin." (PMID 38473429, 2024).
colorectal cancer (4 papers, 2011 to 2025). A primary or metastatic malignant neoplasm that affects the colon or rectum. "Cancer‐associated fibroblast (CAF)‐derived VTN upregulates SLC6A8 expression in colorectal cancer (CRC) cells and macrophages through enhanced FAK phosphorylation." (PMID 40538300, 2025). "ARP3, and VTN were observed to be overexpressed in clinical metastasis colorectal cancer tissues." (PMID 26175278, 2015). "Vitronectin is substantially enriched in the sites of inflamed, injured, necrotic, and cancer tissues including cirrhotic liver, atherosclerotic plaques, injured skin, Alzheimer plaques, myocardial infarction, and colorectal carcinoma." (PMID 21573223, 2011). "Taken together, integrin β5 promotes colorectal cancer cell proliferation by mediating adhesion and cell spreading on vitronectin-coated surfaces and plays this role regardless of its localization in FAs or FCLs." (PMID 35532004, 2022).
endometriosis (4 papers, 2014 to 2022). The growth of functional endometrial tissue in anatomic sites outside the uterine body. "ITGAV is an integrin, that mediates binding to fibronectin, vitronectin, fibrinogen and is upregulated in women with endometriosis when compared to healthy women during menstruation." (PMID 32824678, 2020). "Vitronectin expression was also discovered in patients suffering from endometriosis and infertility." (PMID 25231141, 2014). "Increase of vitronectin and tenascin in certain cancers led to the postulation that the progression of endometriosis was similar to tumor formation." (PMID 24900998, 2014).
ischemic stroke (4 papers, 2019 to 2024). A stroke disorder caused by obstruction of blood flow to the brain, due to thrombotic (local blood clot formation) or embolic (due to a blood clot or other material traveling from another site) event. "It has also been reported that microglia activated by FN1 and VTN promote the progression of ischemic stroke." (PMID 32466277, 2020). "Our results showed that FN1 and VTN levels were higher in ischemic stroke patients than in healthy controls, which was consistent with previous studies." (PMID 32466277, 2020). "We also confirmed that thrombospondin-1 and vitronectin are expressed on circulating endogenous EVs in human ischemic stroke." (PMID 31676801, 2019). "FN1 and VTN activate microglia when brain damage occurs due to conditions such as ischemic stroke." (PMID 32466277, 2020). "Adult female C57BL/6 mice with a 30 min MCAO ischemic stroke showed increases relative to naïve females in blood plasma VTN protein levels at 24 h, but not 3 h, after the cessation of the MCAO." (PMID 35531929, 2022).
liver disease (4 papers, 2006 to 2019). "The elevated levels of LGALS3BP and vitronectin (VTN), another extracellular matrix (ECM) protein, are likely a reflection of remodeling of the ECM in liver disease." (PMID 30824564, 2019).
lung fibrosis (4 papers, 2018 to 2025). "Mutation studies of plasminogen activator inhibitor 1 (PAI-1) have previously implied that PAI-1 promotes lung fibrosis via a vitronectin-dependent (VTN-dependent) mechanism." (PMID 40299646, 2025). "In the present study, we interrogated the importance of VTN to the profibrotic activity of PAI-1 using 2 distinct lung fibrosis models." (PMID 40299646, 2025). "Consistently, PAI-1 binding to vitronectin has been previously shown to inhibit cell migration, leading to inefficient alveolar repair following injury and favoring the development of pulmonary fibrosis." (PMID 34456926, 2021). "The occurrence and progression of lung fibrosis, the extracellular matrix-related molecules such as integrins and their ligands including fibronectin, vitronectin, laminin, and collagens, all play important roles." (PMID 31130697, 2019). "VTN played a positive role in the lung fibrosis of RILT, possibly through modulation of fibrosis regulatory pathways and up-regulating the expression levels of fibrosis-related genes." (PMID 29661186, 2018). "Although it is difficult to assess the role of vitronectin in silicosis from these reports, it may play some role in the development of silica-induced lung fibrosis." (PMID 31130697, 2019). "Reconstitution of PAI-1–/–:VTN–/– mice with PAI-1RR, as in the AEC2 injury model, worsened lung fibrosis as assessed by hydroxyproline and lung histologic analysis that revealed more extensive fibrotic lesions in H&E- and Picrosirius red–stained sections." (PMID 40299646, 2025). "In conclusion, our study showed that VTN played an important role in RILT via up-regulating the expression of collagen, activating the fibrosis regulatory pathway to promote lung fibrosis." (PMID 29661186, 2018). "The experimental results suggested that overexpression of VTN promoted the expression of collagen I, collagen III, hydroxyproline, α-SMA and TGF-β in vivo, which further activated the regulatory pathways of lung fibrosis, and eventually aggravated RILT." (PMID 29661186, 2018). "Furthermore, overexpression of VTN significantly increased the expression level of α-SMA, as well as the degree of lung fibrosis in mice at 8 and 12 weeks post-irradiation." (PMID 29661186, 2018).
glaucoma (3 papers, 2017 to 2024). Increased pressure in the eyeball due to obstruction of the outflow of aqueous humor. "The ECM gene expression levels were significantly lower in untreated normal LC cells than those of untreated glaucoma LC cells for all tested genes including Col1A1, αSMA, fibronectin, and vitronectin." (PMID 39273058, 2024). "Supporting these findings, two membrane attack complex (MAC) assembly endogenous inhibitors, vitronectin and clusterin, were also found to be upregulated in glaucoma." (PMID 28978942, 2017).
interstitial lung disease (3 papers, 2009 to 2018). A diverse group of lung diseases that affect the lung parenchyma. "In the respiratory system, vitronectin has been found in exhaled breath condensate and bronchoalveolar lavage fluid of control individuals and subjects with interstitial lung disease." (PMID 25768308, 2015). "Elevated levels of vitronectin another glycoprotein have also been shown in BAL fluid of patients with interstitial lung disease compared to healthy volunteers." (PMID 19389250, 2009). "The primary cellular source of vitronectin is hepatocytes; it is not known whether resident cells of airways produce vitronectin, even though the glycoprotein has been found in exhaled breath condensate and bronchoalveolar lavage from healthy subjects and patients with interstitial lung disease." (PMID 25768308, 2015).
lung carcinoma (3 papers, 2015 to 2021). "Vitronectin RNA expression in samples of patients with lung cancer or lung infection was not different compared to the control group (p = 0.281, 95% CI, 0.634–1.159)." (PMID 25768308, 2015).
malaria (3 papers, 2012 to 2020). Malaria is a serious and sometimes fatal disease caused by a parasite that commonly infects a certain type of mosquito which feeds on humans. "Uptake of protein S, prothrombin, and vitronectin was also observed in the blood samples prepared from mice infected with the rodent malaria parasite Plasmodium yoelii, suggesting that similar uptake mechanisms are present among Plasmodium spp." (PMID 32295584, 2020). "Quite a few differentially abundant proteins such as Haptoglobin (HP), Superoxide dismutase (SOD), Ceruloplasmin (CP), Titin (TTN), Nebulin (NEB), and Vitronectin (VTN) were found to be highly relevant in context of pathophysiology of severe malaria." (PMID 27090372, 2016). "Our results suggest that Superoxide dismutase, Vitronectin, Titin, Apolipoprotein E, Serum amyloid A, and Haptoglobin are potential predictive markers for malaria severity." (PMID 27090372, 2016).
multiple sclerosis (3 papers, 2012 to 2014). A progressive autoimmune disorder affecting the central nervous system resulting in demyelination. "Vitronectin has been detected in active multiple sclerosis plaques and a decrease in Shh levels has been observed in the white matter of patients with multiple sclerosis." (PMID 23155445, 2012).